FTO (FTO alpha-ketoglutarate dependent dioxygenase)
Diseases named in the same sentence as FTO in open-access papers (continued):
Sharing a sentence is not in itself a finding about the gene and the disease.
acute myeloid leukemia (continued). "In specific subtypes of acute myeloid leukemia (AML), elevated FTO levels decrease m6A levels in ASB2 and RARA mRNA transcripts, thereby promoting their expression." (PMID 40000966, 2025). "For example, in acute myeloid leukemia (AML), inhibiting the demethylase FTO can suppress the expression of immune checkpoint molecules PD-L1 and LILRB4, inducing T-cell cytotoxicity against tumor cells." (PMID 39726589, 2024). "A series of small-molecule compounds targeting FTO is developing therapeutic option in acute myeloid leukemia (AML)." (PMID 38414063, 2024). "As the m6A “eraser”, FTO is the first evidence of the biological effects of m6A modulatory genes on acute myeloid leukemia (AML)." (PMID 38057853, 2023). "m6A demethylase FTO is highly expressed and plays a critical oncogenic role in acute myeloid leukemia (AML) by targeting a cohort of critical transcripts, such as ankyrin repeat and SOCS box-containing 2 (ASB2) and retinoic acid receptor alpha (RARA)." (PMID 36835633, 2023). "It is generally believed that internal m6A modifications in mRNAs are the major substrates of FTO in many cell types studied so far, including acute myeloid leukemia (AML) cells and melanoma cells." (PMID 37192910, 2023). "It has been demonstrated that FTO expression is deregulated in a variety of tumors, including acute myeloid leukemia (AML), gastric cancer (GC), cervical squamous cell carcinoma (CSCC), ovarian cancer (OC), and BC." (PMID 36035182, 2022). "The elevated expression of FTO promotes the proliferation and metastasis in acute myeloid leukemia (AML) cells." (PMID 34103054, 2021). "Likewise, FTO plays a carcinogenic role in acute myeloid leukemia as an m6A demethylase." (PMID 33879631, 2021). "Besides, overexpression of FTO in acute myeloid leukemia cells could decrease m6A modification of NANOG and SOX2 and increase their mRNA levels, which was consistent with our studies in HCC cells." (PMID 33783988, 2021). "For instance, the overexpression of FTO in acute myeloid leukemia (AML) can inhibit the m6A levels of Ankyrin repeat and SOCS box containing 2 (ASB2) and of retinoic acid receptor α (RARα) mRNA, resulting in the occurrence and progression of AML." (PMID 33643384, 2021). "FTO is the first m6A demethylase that is highly expressed in acute myeloid leukemia (AML), and it plays a critical oncogenic role." (PMID 31619268, 2019). "Similarly, upregulation of FTO is necessary for its oncogenic role in acute myeloid leukemia." (PMID 30953473, 2019). "CEBPA is identified as an exclusive transcription factor displaying a positive correlation with FTO and regulating its transcription in acute myeloid leukemia (AML)." (PMID 31142332, 2019). "In MLL-rearranged acute myeloid leukemia (AML), FTO is highly expressed, promotes oncogene-mediated cell transformation and leukemogenesis, and inhibits all-trans-retinoic acid (ATRA)-induced AML cell differentiation." (PMID 29061143, 2017). "Potential drugs such as CS1, CS2, and NSC48890, suggested for acute myeloid leukemia, and imidazobenzoxazin-5-thione (MV1035) aiming for tumor immunity target the inhibition of FTO and ALKBH5, respectively." (PMID 39629934, 2025). "Other FTO inhibitors reported were obtained after in silico virtual screenings, including oxetanyl inhibitors in GBM cells and CS1 and CS2 in acute myeloid leukemia cells." (PMID 40002173, 2025). "Meclofenamic acid has been proven to be a specific inhibitor of FTO compared to ALKBH5, showing increased m6A levels and reduced proliferation in acute myeloid leukemia and GSCs." (PMID 40002173, 2025). "In acute myeloid leukemia (AML), TP53INP2 is upregulated by FTO-mediated modification of m6A, which enhances autophagy activity by promoting the interaction of LC3 and ATG7, ultimately promoting leukemia cell survival." (PMID 38576024, 2024).
acute myeloid leukemia (continued). "Since FTO is involved in the occurrence and poor prognosis of various cancers, such as glioblastoma (GBM) and acute myeloid leukemia (AML), FTO inhibitors are thought to be a promising cancer targeted therapy." (PMID 37055798, 2023). "Small molecule inhibitors of FTO, FB23, and FB23-2, strongly inhibited human acute myeloid leukemia cell growth, showing a powerful antitumor effect." (PMID 37028765, 2023). "In acute myeloid leukemia (AML), m6A within mRNA is the predominant substrate of FTO." (PMID 35023630, 2022). "STM2457 and FB23/FB23-2 were small-molecular inhibitors of m6A regulators, preventing the development of human acute myeloid leukemia cells in vitro by specifically suppressing the activities of METTL3 and FTO, respectively, in recent research." (PMID 36120320, 2022). "In addition, FTO, as an m6A demethylase, has been found to play an important role in carcinogenesis in acute myeloid leukemia (AML)." (PMID 33952279, 2021). "Meclofenamic acid 2 (MA2), a selective inhibitor of FTO, exerted substantial inhibitory effects on the growth of glioblastoma stem-like cells (GSC) and acute myeloid leukemia (AML) in mice xenograft model." (PMID 32209098, 2020). "For example, the m6A eraser FTO is highly expressed in acute myeloid leukemia (AML)." (PMID 31804607, 2020). "Chen and He groups showed an oncogenic role of FTO in acute myeloid leukemia (AML)." (PMID 30922314, 2019). "FTO was found to play an oncogenic role in acute myeloid leukemia (AML)." (PMID 28533023, 2017). "Additionally, downregulation of FTO could inhibit the proliferation and differentiation capacity through reducing the abundance of m6A in acute myeloid leukemia (AML)." (PMID 35154270, 2022). "FTO plays its major role through reducing the abundance of internal m6A modification, especially in the 3′ untranslated regions (3′-UTRs), which in turn leads to decreased stability of the target mRNA transcripts and influences the occurrence and progression of acute myeloid leukemia (AML)." (PMID 33692753, 2021). "Moreover, FTO promotes proliferation of AML cells through targeting of the ASB2 and RARA in acute myeloid leukemia cells." (PMID 31333841, 2019). "A recent study reported that O-GlcNAcylation of FTO at the Ser173 site promotes myelodysplastic syndromes (MDS) and acute myeloid leukemia (AML) cell proliferation." (PMID 40642069, 2025). "For example, inhibition of FTO expression using FB23 and FB23-2 affects cell cycle and apoptosis in acute myeloid leukemia (AML), which can significantly damage the growth and proliferation of cancer cells, and then achieve the purpose of cancer therapy." (PMID 39033180, 2024). "In acute myeloid leukemia (AML), abnormal expression of m6A regulatory factors, including METL3, METTL14, FTO, ALKBH5, and IGF2BP1/2/3, can regulate the expression of MYC." (PMID 33926508, 2021). "The mutations of m6A regulatory genes, METTL3, METTL14, YTHDF1, YTHDF2, FTO, and ALKBH5, have been identified in acute lymphoblastic leukemia, multiple myeloma, and acute myeloid leukemia (AML)." (PMID 33898522, 2021). "In acute myeloid leukemia (AML), mimicking FTO depletion, an FTO inhibitor FB23-2 significantly inhibited the proliferation of human AML cell lines and primary cells in vitro and promoted cell differentiation/apoptosis." (PMID 32547941, 2020). "We hypothesized that FTO and ALKBH5 play crucial proleukemogenic roles in T-ALL, akin to their functions in acute myeloid leukemia (AML)." (PMID 40435251, 2025). "Additionally, FTO has been identified as having an oncogenic role in multiple cancers, and it targets LILRB4 in acute myeloid leukemia (AML) cells." (PMID 38397424, 2024). "Furthermore, in acute myeloid leukemia (AML), FTO inhibition can lead to downregulation of leukocyte immunoglobulin-like receptor subfamily B member 4 (LILRB4), render AML cells vulnerable to activated T cells, and simultaneously overcome hypomethylating agent (HMA)-induced immune evasion." (PMID 34988083, 2021).
acute myeloid leukemia (continued). "Importantly, FTO knockdown does not influence cell growth, which differs from the AML (acute myeloid leukemia) model." (PMID 33741917, 2021). "This study found that a negative correlation between FTO expression and O-GlcNAcylation in patients with myelodysplastic syndrome (MDS) and acute myeloid leukemia (AML)." (PMID 39849461, 2025).
melanoma (146 papers, 2013 to 2026). A malignant, usually aggressive tumor composed of atypical, neoplastic melanocytes. "In melanoma, FTO variations are associated with a high risk of tumor development and progression, without any association with increased body mass index." (PMID 40427015, 2025). "In contrast, demethylase FTO has an adverse impact on NK cells, and the specific reduction of FTO results in increased NK cell activation and a decreased risk of melanoma progression." (PMID 39904996, 2025). "FTO has recently been shown to regulate the immune response to melanoma and skin tumorigenesis caused by arsenic and UVB irradiation." (PMID 39872957, 2023). "The role of the m6A eraser FTO in cancer was first demonstrated in melanoma, where specific FTO variants were associated with increased melanoma risk in a BMI-independent manner." (PMID 37612540, 2023). "In melanoma, overexpression of FTO is associated with increased growth, proliferation, cell migration, and invasion." (PMID 35515106, 2022). "It has been consistently proven that loss of FTO sensitizes melanoma cells to interferon-γ and sensitizes melanoma to anti-PD-1 treatment in mice, which depends on adaptive immunity." (PMID 36071523, 2022). "Earlier findings from 2013 suggested that FTO genetic variations were associated with an increased risk of melanoma." (PMID 35628623, 2022). "For the melanoma cells, the fat mass and obesity-associated protein (FTO) is the first m6A demethylase identified." (PMID 36384676, 2022). "FTO-mediated m6A modification was also associated with drug resistance in various cancers, such as MM, glioblastoma, and melanoma." (PMID 36517820, 2022). "FTO expression is regulated by autophagy pathway and nuclear factor kappa B pathways and can be induced by metabolic stress; the FTO protein itself regulates the expression of known melanoma-related genes encoding PD-1 (PDCD1), CXCR4, and SOX10." (PMID 34105069, 2021). "Two mechanisms were proposed, through single-nucleotide polymorphisms outside of intron one (body mass index-related region), as rs16953002, the variant of intron 8 of FTO that has been reported to be associated with a high risk of melanoma." (PMID 33511112, 2020). "In melanoma, fat mass and obesity-associated protein (FTO), a N-methyladenosine (mA) demethylase, plays an important role in promoting tumor resistance to Anti-PD-1." (PMID 33344447, 2020). "Recent work has also suggested that the genetic variations of FTO are associated with increased melanoma risk in humans." (PMID 31239444, 2019). "To determine the biological function of FTO in melanoma cells, we performed both gain- and loss-of-function studies in melanoma cells." (PMID 31239444, 2019). "A recent study have demonstrated that mutations within intron 8 of FTO leads to increased melanoma risk, suggesting a link between m6A and melanoma." (PMID 28027310, 2016). "Recently, an independent effect at the eighth intron of the FTO locus has been reported to be associated with melanoma." (PMID 24348519, 2013). "Studies have also found an association between FTO SNPs and melanoma susceptibility." (PMID 40722726, 2025). "Downregulation of FTO could induce melanoma cells more sensitive to IFN‐γ and more susceptible to PD‐1 treatment." (PMID 36324258, 2022). "In addition, we found a positive association between FTO and PD-1 protein levels in Mel624 cells and human melanoma tissue." (PMID 31239444, 2019). "PD-1 (PDCD1) mRNA expression is positively associated with FTO expression in melanoma." (PMID 31239444, 2019). "FTO silencing increased the sensitivity of melanoma cells to IFN-γ and enhanced the sensitivity of melanoma to anti-PD1 therapy in murine models." (PMID 41522342, 2026). "In melanoma cells, knocking down the FTO gene can accelerate the RNA degradation rate of intrinsic pro-tumor genes including PD-1, CXCR4 and SOX10 through YTHDF2." (PMID 40675967, 2025).
melanoma (continued). "Under metabolic stress, melanoma cells increase the level of FTO through autophagy and NF-κB signaling pathways, resulting in resistance to interferon-γ (IFN-γ) and anti-PD-1 treatment." (PMID 40675967, 2025). "As for erasers, FTO can promote anti-PD-1 resistance by modulating m6 A methylation in several vital protumorigenic melanoma cell-intrinsic genes, PD-1, SOX10, and CXCR4." (PMID 40483535, 2025). "FTO gene modulation and RNA methylation changes can sustain a better response to therapy in the case of melanoma." (PMID 40427015, 2025). "There have been reports that FTO, an alpha-ketoglutarate dependent dioxygenase, induced resistance to aiti-PD-1 therapy in melanoma." (PMID 38627760, 2024). "Similar mechanisms have been observed in melanoma and rectal cancer studies, where FTO downregulation led to increased m6A methylation levels in key genes, resulting in enhanced RNA degradation by YTHDF2." (PMID 38995602, 2024). "In melanoma cells, downregulation of FTO reduces the removal of m6A modifications on PD-1, affecting mRNA decay and inhibiting tumor growth." (PMID 39726589, 2024). "In melanoma cells, FTO increased the RNA stability of programmed cell death 1 ligand 1 (PD-L1) by inducing m6A demethylation, and prevented PD-L1 from being recognized by YTHDF238." (PMID 38438714, 2024). "Functionally, FTO generally acts as an oncogene in different cancers, such as glioblastoma and melanoma, emphasizing the potential of targeting FTO as a therapeutic approach against cancer." (PMID 39136000, 2024). "In melanoma, FTO knockdown increases m6A methylation of key oncogenes like PD‐1, CXCR4 and SOX10, promoting YTHDF2‐mediated mRNA degradation and making melanoma cells more susceptible to interferon‐γ and anti‐PD‐1 therapy." (PMID 39135292, 2024). "The inhibition of FTO suppresses melanoma cell tumorigenicity and expression of melanoma cell-intrinsic genes, including PD1; this treatment sensitizes melanoma cells to anti-PD1 therapy in mice." (PMID 39329974, 2024). "Melanoma tumorigenesis and anti-PD-1 resistance are promoted by m6A mRNA demethylase FTO, which is induced by metabolic starvation stress through the autophagy and NF-κB pathways." (PMID 37063421, 2023). "FTO-mediated m6A demethylation promoted melanoma growth and reduced the response to anti-PD-1 immunotherapy." (PMID 37264402, 2023). "The oncogenic function of FTO in melanoma is manifested by increased tumor growth and inhibited host responses to anti-PD-1 therapy." (PMID 36810108, 2023). "FTO promotes melanoma processing and anti-PD-1 resistance, and suggests the potential of the combination of FTO inhibition with anti-PD-1 blockade in resistance to immunotherapy." (PMID 37063421, 2023). "For example, FTO was entrusted crucial role as an m6A demethylase in promoting melanoma tumorigenesis and anti-PD-1 resistance." (PMID 37840133, 2023). "In melanoma, Dac51 enhances m6A modification levels in JunB and C/EBPβ mRNA by inhibiting FTO, which facilitates the binding of YTHDF2 to both mRNAs, leading to significant reductions in JunB and C/EBPβ expression." (PMID 37582735, 2023). "It has been reported that FTO decreased the drug resistance of melanoma and cervical squamous cell carcinoma through mRNA demethylation." (PMID 37402730, 2023). "Herein, inhibition of FTO promotes T cell infiltration and synergizes with anti-PD-L1 blockade in melanoma." (PMID 36810281, 2023). "The FTO gene as an m6A demethylase was determined to play a crucial role in enhancing melanoma tumourigenesis and anti‐PD‐1 resistance." (PMID 34647424, 2022). "In melanoma, inhibition of FTO suppresses tumorigenicity and increases the m6A levels in PD-1, CXCR1, and SOX10, hence enhancing the decay of these m6A-targeted mRNAs by YTHDF2." (PMID 35254013, 2022). "FTO can reduce the enrichment of m6A in key melanoma promoting genes, including PD-1 (PDCD1), CXCR4 and SOX10, and maintain their mRNA stability." (PMID 35590394, 2022).